AFP (alpha fetoprotein)
Diseases named in the same sentence as AFP in open-access papers (continued):
Sharing a sentence is not in itself a finding about the gene and the disease.
Cirrhosis (continued). "The rs422951 CC genotype was associated with increased risk of death in the following subgroups: age >45 years, smoking status, AFP >400 ng/mL, non‐PVTT, Child‐Pugh B, cirrhosis, BCLC stages B and C, nonadjuvant TACE, regional invasion, and intrahepatic metastasis." (PMID 28568708, 2017). "In addition, plasma CCT3 and IQGAP3 from 38 AFP-negative HCC and 88 cirrhosis patients were analyzed." (PMID 27390551, 2016). "In the group composed of the patients without cirrhosis (group 1), those who had higher levels of initial AST, total bilirubin, and AFP achieved a greater reduction of LSM value than those had lower levels of initial AST, total bilirubin, and AFP." (PMID 24682088, 2014). "Another marker that was significantly elevated in advanced liver fibrosis was alpha-fetoprotein (AFP) (P = 0.0019), which has previously been shown to be elevated in HCV patients with cirrhosis and is a clinical marker of HCC, although none of our patients had been diagnosed with HCC at present." (PMID 23840845, 2013). "Although AFP is not specific for HCC and may be seen clinically in nonmalignant conditions such as chronic hepatitis, cirrhosis or fulminate hepatic failure, the elevation of AFP and confirming ultrasound findings clearly indicate malignant disease." (PMID 24281167, 2010). "Importantly, miR-21 remained effective even in AFP-negative HCC cases (AUC ~0.83) and could differentiate HCC from chronic hepatitis B (AUC ~0.79) or cirrhosis (AUC ~0.81)." (PMID 41007803, 2025). "In addition, we found that the level of Sphingosine (d18:1)-1-P is not correlated with AFP concentration in patients with cirrhosis or HCC, suggesting that the regulatory mechanism of Sphingosine (d18:1)-1-P in HCC patients may be independent of AFP." (PMID 33014866, 2020). "The combination of PTX3 with AFP, although slightly increased AUC values, did not significantly increase the performance of PTX3 for discriminating late-stage HCC from chronic hepatitis (AUC 0.965), cirrhosis (AUC 0.944) or chronic HBV infection without HCC (AUC 0.956)." (PMID 33219288, 2020).
liver cancer (829 papers, 2002 to 2026). An epithelial or non-epithelial malignant neoplasm that arises from the liver. "AFP levels > 400 ng/mL were significantly associated with primary liver cancer (63.6% vs. 4.8%, p < 0.001)." (PMID 39857748, 2025). "Alpha-fetoprotein levels were significantly higher in ET-P compared with ET-B, consistent with findings from liver cancer patients showing positive associations between AFP levels and Prevotella abundance." (PMID 41244669, 2025). "AFP is not only a diagnostic marker in liver cancer but also a multifunctional molecule driving tumor progression." (PMID 40458724, 2025). "Serum AFP levels > 400 ng/mL were significantly associated with primary liver cancer (63.6% vs. 4.8%, p < 0.001)." (PMID 39857748, 2025). "It achieves a response time of approximately 15 min and exhibits high selectivity for AFP, a biomarker associated with liver cancer, while effectively discriminating against other biomarkers such as PSA and CEA." (PMID 39996991, 2025). "Alpha-fetoprotein blood test: When attempting to identify individuals at high risk of liver cancer at an early stage, the alpha-fetoprotein blood test is occasionally used with hepatic ultrasound imaging." (PMID 40078237, 2025). "Elevated alpha-fetoprotein (AFP) levels are used as a diagnostic marker for liver cancer and to monitor disease progression." (PMID 40831536, 2025). "In most literature, AFP is closely linked to the recurrence of liver cancer, which makes it more relevant to DFS." (PMID 41180318, 2025). "Although alpha-fetoprotein (AFP) is commonly employed for detecting and monitoring liver cancer, its diagnostic utility is hindered by limited sensitivity." (PMID 40918463, 2025). "The main serological biomarker of liver cancer is serum AFP, which is the most commonly used diagnostic method at present." (PMID 39650722, 2024). "Subsequent investigations should elucidate the precise mechanism underlying the interaction between AFP and LCSCs and explore intervention approaches targeting AFP to enhance the treatment effect of liver cancer." (PMID 38660138, 2024). "In South Korea, liver cancer screening is offered to high-risk individuals aged 40 years and older using an abdominal ultrasonography plus serum alpha-fetoprotein test." (PMID 38238704, 2024). "Approximately 70% of patients with HCC express and secrete the glycoprotein AFP, which is widely regarded as being associated with the biological behavior of liver cancer." (PMID 39767676, 2024). "In ascites caused by primary liver cancer metastasis, AFP levels are commonly elevated; CA19-9 is highly correlated with pancreatic cancer, gallbladder cancer, colorectal cancer, and gastric cancer." (PMID 39737405, 2024). "It is especially noteworthy taking into account the varied origins of the samples, the preponderance of early-stage liver cancer samples and samples with blood alpha-fetoprotein (AFP) levels below the commonly used diagnostic threshold of 400 ng/ml." (PMID 37798661, 2023). "CYP metabolites have also been associated with the liver cancer diagnostic marker alpha-fetoprotein (AFP)." (PMID 37238655, 2023). "tested the diagnostic ability of PITX1 for liver cancer (n = 63) and compared it with the AFP group." (PMID 37841446, 2023). "Higher expression level of M17 (cell cycle) was associated with increased vascular invasion, higher serum alpha-fetoprotein, and more advanced tumour grade and Barcelona Clinic Liver Cancer stage." (PMID 37648284, 2023). "Studies have found that high AFP expression in the serum or tumor cells indicates poor prognosis and is associated with vascular invasion, high tumor grade, and bulky liver cancer." (PMID 37283795, 2023). "Traditional biomarkers for the prognosis, diagnosis, and monitoring of liver cancer, such as alpha-fetoprotein, have limitations not only in terms of the underlying mechanisms at the surveillance stage, but also in predicting late clinical outcomes." (PMID 37313461, 2023).
liver cancer (continued). "For example, alpha-fetoprotein (AFP) is commonly used as a diagnostic marker for liver cancer patients." (PMID 37366982, 2023). "Alpha-fetoprotein (AFP) is a widely used biomarker for the diagnosis of liver cancer, but its diagnostic accuracy is limited because it has a high false-negative rate in the detection of small tumors and early tumors." (PMID 36119529, 2022). "Alpha-fetoprotein (AFP) is a recognized diagnostic marker for liver cancer, but its specificity and sensitivity are poor when used alone." (PMID 35549979, 2022). "It is well known that AFP is the most widely used serum biomarker for the diagnosis of primary liver cancer worldwide and is associated with poor prognosis." (PMID 36338652, 2022). "Albumin level below the cohort median (3.4 g/dL) emerged as an independent risk factor for TTP controlling for AFP > 20 ng/mL as well as Milan, T-stage, and Barcelona Clinic Liver Cancer (BCLC) stage individually." (PMID 35406456, 2022). "The liver cancer diagnostic accuracy of miR-206 and miR-126 combined was similar to that of AFP based on comparative ROC curve analysis." (PMID 35943150, 2022). "Individuals at the highest risk of developing liver cancer are most likely to benefit from active surveillance using liver ultrasonography and serum alpha-fetoprotein test." (PMID 36261855, 2022). "Previous literature had reported that underweight (BMI <18.5 kg/m2) and increased AFP were associated with increased mortality from liver cancer." (PMID 35252202, 2022). "This sensitivity rate, however, was much greater than for the currently-recommended AFP diagnostic guidelines for liver cancer of ≥ 400 ng/mL." (PMID 36241994, 2022). "The expression of DNAJA1 was associated with clinicopathologic features in liver cancer and correlated strongly with differentiation (P < 0.001), dissemination (P < 0.001), and serum AFP (P = 0.020)." (PMID 35586205, 2022). "As an oncofetal antigen and a diagnostic marker for HCC, AFP has long been recognized as a useful predictor of the prognosis of liver cancer." (PMID 36016629, 2022). "We investigated the factors associated with TERT C228T and abnormal levels of liver cancer-specific tumor markers (AFP and PIVKAII) in serum samples." (PMID 35306637, 2022). "Nevertheless, a previous study demonstrated that serum CCT3 was a potential biomarker of liver cancer with a better diagnostic capacity than AFP in certain regards." (PMID 35073517, 2022). "Like traditional liver cancer markers alpha-fetoprotein and CA19-9, 9,12-octadecadienoic acid associated liver function indicators, GGT and ALP, have also been found to be related to the occurrence and progression of liver cancer." (PMID 35637430, 2022). "Binary logistic regression analysis determined that AFP and CA-125 were associated with liver cancer metastasis." (PMID 36199582, 2022). "EpCAM is a well-characterized surface marker of liver cancer cells, and the presence of EpCAM-positive CTCs has been previously associated with vascular invasion, increased serum AFP, more advanced HCC stage, and increased recurrence rates after surgery." (PMID 34069569, 2021). "AFP was discovered 50 years ago as a diagnostic biomarker of liver cancer and currently, there are problems associated with the inaccuracy of diagnosis." (PMID 34238253, 2021). "Similar to the result of a former large-scale, multicenter clinical trial, we found that plasma Hsp90α exhibited a significantly higher diagnostic performance for liver cancer than AFP." (PMID 34348726, 2021). "MVI and AFP have been proved as independent risk factors of early recurrence and poor overall survival after liver cancer liver resection; the correlation between them has been dramatically focused." (PMID 33816254, 2021). "The purposes of this study were to assess the correlation between the plasma level of Hsp90α and the clinicopathological characteristics of patients with liver cancer and compare the diagnostic efficacy of Hsp90α, AFP, CEA, and CA199 in HCC." (PMID 34348726, 2021).
liver cancer (continued). "It is known that approximately 50% of HCCs secrete AFP, which is not only an oncofoetal antigen and diagnostic marker for liver cancer but also an independent risk predictor associated with pathological grade, progression, and survival outcome." (PMID 34496797, 2021). "At present, alpha-fetoprotein (AFP) is a diagnostic biomarker used in the clinical diagnosis of liver cancer." (PMID 34238253, 2021). "We used TERT promoter mutations and miR-122 in the combination with AFP in the predictive models based on the evidence on clinical relevance of these biomarkers in the association with liver cancer." (PMID 32424223, 2020). "The area under the receiver operating characteristic curve (AUC-ROC) analysis indicated that serum RRM2 (AUC: 0.863, 95% CI 0.821–0.904) was a better diagnostic marker of liver cancer than AFP (AUC: 0.798, 95% CI 0.745–0.851)." (PMID 33372599, 2020). "It should be noted that the presence of miR-122 and miR-224 is associated with AFP, alkaline phosphatase level and tumor size,and they can be considered as biomarkers for early detection of liver cancer." (PMID 33585001, 2020). "Meanwhile, AFP has been associated with liver cancer 30, and CEA is a broad-spectrum tumor marker used to assess the progression and prognosis of colorectal cancer 31, breast cancer 32, and lung cancer." (PMID 32226491, 2020). "In this study, we confirmed the pro-oncogenic role of AFP in liver cancer development using an AFP-deficient mouse model." (PMID 33009373, 2020). "Higher serum AFP level was significantly associated with iCluster (Chi-square: 16.86, P = 0.0002) of liver cancer." (PMID 31897235, 2020). "In majority of liver cancer patients, the expression of AFP is reactivated, therefore, AFP has been generally accepted as a diagnostic and prognostic biomarker for liver cancer since 1970s38,39." (PMID 32433581, 2020). "Using flow cytometry, we further confirmed the expression of liver cancer-associated markers such as AFP, GPC3 and carcinoembryonic antigen (CEA) in miPS-Huh7cmP1 cells in comparison with Nanog." (PMID 32203212, 2020). "First, the expression levels of liver cancer-associated markers, AFP, GPC3 and CK19 as well as liver CSC markers, CD44, CD24 and CD133, in malignant tumours were relatively high compared to that in normal liver by RT-qPCR." (PMID 32203212, 2020). "Generally, the AFP level exceeding the threshold of 25 ng mL−1 in serum is suspected to be associated with the occurrence of liver cancer or other related diseases." (PMID 30935114, 2019). "HCC is the most common type of primary liver cancer in adults and is the most common cause of death in people with cirrhosis, and AFP is still considered to be the gold standard biomarker of HCC, although it has been challenged due to the lack of sensitivity." (PMID 29954402, 2018). "As an oncofetal antigen and diagnostic marker for liver cancer, alpha-fetoprotein (AFP) possesses a variety of biological functions." (PMID 29805966, 2018). "Two studies investigated biannual testing of serum alpha fetoprotein to screen for liver cancer in high–risk subjects." (PMID 29250323, 2017). "From an initial sample of 105,806 patients identified with liver cancer, 3796 fulfilled our eligibility criteria for evaluating the association of AFP levels with pathological grades." (PMID 28993684, 2017). "Alpha-fetoprotein (AFP) is a liver cancer associated protein and has long been utilized as a serum tumor biomarker of disease progression." (PMID 26497223, 2015). "Eastern countries, such as Japan and Korea, recommend abdominal ultrasonography combined with measurements of tumor markers, such as AFP, for groups at high risk of liver cancer." (PMID 23840846, 2013). "While various imaging modalities can be applied to diagnosis of primary liver cancer, the main diagnostic test remains measurement of α-fetoprotein (AFP), the best accepted serum tumour marker for HCC, in addition to imaging." (PMID 12799633, 2003).
liver cancer (continued). "Measurement of serum AFP and hepatic ultrasonography are widely used as surveillance modalities for patients with high-risk of liver cancer." (PMID 12454776, 2002). "AFP was initially established as a diagnostic biomarker for primary liver cancer." (PMID 40900791, 2025). "Elevated AFP levels are associated with a poorer prognosis in liver cancer patients." (PMID 39583507, 2024). "Interestingly, serum HSP90 exhibited potential as either a diagnostic or a stage predictive biomarker in liver cancer patients compared to alpha fetoprotein." (PMID 39768997, 2024). "As we all know, serum AFP is the currently available diagnostic test for liver cancer." (PMID 36713030, 2023). "The level of AFP in serum can be used to screen high-risk populations (e.g., those with a family history or occupational exposure to carcinogens), assist in early detection and diagnosis of liver cancer, monitor treatment efficacy, and predict prognosis." (PMID 37836778, 2023). "Body mass index (BMI) (P = 0.022), alpha-fetoprotein (P = 0.023), total bilirubin (P = 0.016), intraoperative blood loss (P < 0.001), and bile leakage (P < 0.001) were independent risk factors for infection after liver cancer surgery." (PMID 37046206, 2023). "Additionally, high level of PD-1/PDL-1 expression was associated with aging, multiple tumors, high alpha-fetoprotein levels, and advanced Barcelona Clinic Liver Cancer stage." (PMID 37047482, 2023). "In order to further verify the causal relationship between air pollution and primary liver cancer, we selected four biomarkers (Alpha-fetoprotein, Osteopontin, Glypican-3 and Arginase-1) which are closely related to primary liver cancer as the outcome and conducted MR Analysis again." (PMID 37575092, 2023). "In addition, serum alpha-fetoprotein (AFP), a biomarker of liver cancer risk, was significantly higher in the e-waste workers compared to the control group (3.56 ± 0.34 vs. 2.14 ± 0.80 ng/mL; p < 0.045)." (PMID 36361155, 2022). "This developed immunosensor could be applied to screening and monitoring of AFP associated with liver cancer." (PMID 36389169, 2022). "At present, the European Liver Association and the American Association for the Study of Liver Diseases no longer recommend the determination of AFP levels for the diagnosis of liver cancer, and there are some doubts regarding the diagnostic sensitivity of AFP." (PMID 35602894, 2022). "At present, the most used clinical diagnostic marker for liver cancer is AFP." (PMID 35397600, 2022). "Among them, the diagnostic combination of exosomes circ_0070396 + AFP could distinguish between the non‐cancerous control and liver cancer with 81.98% sensitivity and 100% specificity." (PMID 35446993, 2022). "AFP has been associated with the development of liver cancer." (PMID 36246602, 2022). "Finally, we determined the value of AFP, CA-125, and AFP + CA-125 as diagnostic indicators for ocular metastasis of liver cancer by binary logistic regression analysis and plotting ROC curves." (PMID 36199582, 2022). "Furthermore, the accuracy of AFP as a diagnostic marker for liver cancer was demonstrated in the clinical samples for comparison." (PMID 35943150, 2022). "AFP is one of the most relevant physiological markers for screening, clinical diagnosis, effectiveness evaluation, and post-treatment monitoring in high-risk populations of liver cancer." (PMID 35784933, 2022). "Other tumor markers, including CEA and AFP, also had a high diagnostic sensitivity, which could therefore also be used to distinguish the liver cancer patients and healthy controls." (PMID 33727662, 2021). "Therefore, a new index was needed to complement AFP in clinical practice so as to improve the early diagnostic rate, therapeutic effect, and prognosis of liver cancer." (PMID 34348726, 2021).